VCAM1 (vascular cell adhesion molecule 1)
Diseases named in the same sentence as VCAM1 in open-access papers (continued):
Sharing a sentence is not in itself a finding about the gene and the disease.
endothelial dysfunction (continued). "In line with the previous results, the present study showed that both captopril and hydralazine, despite having different modes of action, reduce the circulating VCAM‐1 concentrations in SHR suggesting amelioration of the endothelial dysfunction with both anti‐hypertensive therapies." (PMID 39414396, 2024). "Endothelial dysfunction is associated with the overexpression of ICAM-1 and VCAM-1." (PMID 39457107, 2024). "Also, a recent study disclosed that PCB2 ameliorated endothelial dysfunction induced by soluble fms-like tyrosine kinase-1, reduced VCAM-1 expression in HUVECs, and inhibited leukocyte adhesion to HUVECs." (PMID 38679696, 2024). "Markers of endothelial dysfunction may provide more insight into the role of endothelial impairment driving the disease stages; markers include VCAM1, ICAM1, and ET-1." (PMID 37893034, 2023). "Interestingly, VCAM-1 has been reported to have an important role in the development of endothelial dysfunction." (PMID 36717473, 2023). "In addition, TDI01 rescued endothelial dysfunction by downregulating the expression of VCAM1 and ICAM1, attenuating inflammatory cell adhesion and decreasing permeability." (PMID 36969192, 2023). "Endothelial dysfunction has been implicated in thrombotic microangiopathy in patients with severe COVID-19, with increased circulating endothelial cells and plasma levels of soluble ICAM-1, VCAM-1, and P-selectin." (PMID 37896963, 2023). "In addition, AGEs accumulate in atherosclerotic lesions contributing to endothelial dysfunction and up-regulating the expression of vascular cell adhesion molecule-1 (VCAM-1) or intercellular adhesion molecule-1 (ICAM-1)." (PMID 36985650, 2023). "In the present study, LPZ can reduce cardiac and pulmonary VCAM-1 expression which in turn may reduce endothelial dysfunction." (PMID 36717473, 2023). "Several studies have observed in MS elements of endothelial dysfunction, such as an increase in adhesion molecule (i.e., VCAM-1) expression, which might be related to inflammation-driven permeabilization of the BBB." (PMID 36826039, 2023). "In the general population, high levels of endothelial adhesion molecules such as vascular cell adhesion molecule 1 (VCAM-1), intracellular adhesion molecule 1 (ICAM-1) and selectins (P-selectin or E-selectin) have been consistently associated with endothelial dysfunction." (PMID 36821530, 2023). "Therefore, markers of endothelial proinflammatory activation including the cell surface expression of adhesion molecules like VCAM-1 and prothrombotic mediators like vWF are important signs of endothelial dysfunction." (PMID 35906216, 2022). "The endothelial dysfunction was manifested by the induction of proinflammatory cytokines and prothrombotic mediators, like vascular cell adhesion molecule-1 (VCAM-1) and von Willebrand Factor (vWF), along with suppression of endothelial nitric oxide synthase (eNOS)." (PMID 35906216, 2022). "In addition, endothelial dysfunction parameters (Serum sVCAM-1: soluble vascular cell adhesion molecule-1, fibrinogen, and oxidized LDL), apolipoprotein A and apolipoprotein B were significantly (p < 0.001) reversed to near normal following treatment with MLE." (PMID 35893859, 2022). "Furthermore, in conditions of endothelial dysfunction, NO bioavailability is often reduced in relation to increased expression of VCAM‐1 and ICAM‐1 through enhanced reactive oxidative stress in the vessel walls." (PMID 36301720, 2022). "In addition, the elevation of blood pressure and early marker of endothelial dysfunction (vascular cell adhesion molecule-1, VCAM-1) was markedly suppressed in MnSOD-transduced carotid and femoral arteries in a hypertensive rat model." (PMID 36555531, 2022). "In addition, the combination effectively reversed the hyperglycemia-induced endothelial dysfunction in diabetic rats and regulated the expression of eNOS, 3-nitrotyrosine, VCAM-1, CD31 and SIRT-1 markers." (PMID 36496468, 2022).
endothelial dysfunction (continued). "Here, we directly compared both esomeprazole MH and MTH and examined whether esomeprazole MTH can also mediate endothelial dysfunction by examining markers of dysfunction (vascular cell adhesion molecule-1 (VCAM-1) and endothelin-1 (ET-1))." (PMID 36076929, 2022). "TSA prevented the up-regulation of the endothelial dysfunction markers (VCAM-1 and ICAM-1)." (PMID 36362263, 2022). "Vcam1 is a surrogate marker for assessing endothelial dysfunction." (PMID 34957381, 2022). "Both drugs could mitigate expression of the endothelial dysfunction markers, vascular cell adhesion molecule-1 and endothelin-1 (via qPCR)." (PMID 36076929, 2022). "In addition, we explored key markers of endothelial dysfunction, ET-1 and VCAM1, both known to be elevated in preeclamptic pregnancies." (PMID 36076929, 2022). "Moreover, resistin causes endothelial dysfunction by enhancing proinflammatory markers such as MCP-1, TNF-α, IL-6, long pentraxin 3, IL-1β, vascular cell adhesion molecule-1 (VCAM-1), and intercellular adhesion molecule-1 (ICAM-1)." (PMID 35177953, 2022). "In addition, serum VCAM-1 levels correlate with endothelial dysfunction and the initiation and progression of RA42,43,45." (PMID 35264632, 2022). "Also, by downregulating ICAM-1 and VCAM-1, kaempferol can ameliorate endothelial dysfunction and rheumatic disease symptoms." (PMID 36267087, 2022). "The increased expression of VCAM-1 boosts leukocyte adhesion and induces endothelial dysfunction." (PMID 36088760, 2022). "Moreover, this cytokine induces expression of the soluble adhesion molecules ICAM-1 and VCAM-1, markers of endothelial dysfunction." (PMID 35050236, 2022). "In addition, integrated EVOO at a Mediterranean lunch is able to mitigate oxidative stress regulating endothelial dysfunction and platelet oxidative stress, as demonstrated by reduced Nox2 activity and the soluble release of E-selectina/VCAM1, respectively." (PMID 36555645, 2022). "In conclusion, the present study reveals that MSCs-CM significantly attenuates endothelial dysfunction against IR injury in the aorta of BD rats, in part, by lowering inflammatory response (through VCAM-1, ICAM-1 expression regression) and reducing caspase-mediated apoptosis." (PMID 33627181, 2021). "Moreover, PCSK9 has been implicated in endothelial dysfunction by upregulating the expression of intercellular adhesion molecule-1 (ICAM-1) and vascular cell adhesion molecule-1 (VCAM-1) in endothelial cells." (PMID 34336112, 2021). "In this study, the expression levels of MALTA1 and miR-320a in obese children and adolescents before and after exercise were examined, and their correlation with endothelial dysfunction was investigated by evaluating the levels of VCAM-1, ICAM-1, and E-selectin." (PMID 34123418, 2021). "By contrast, VCAM-1 seems to indicate the conditions of the cerebral endothelium and the dendritic cells more precisely and thus could be used to assess endothelial dysfunction." (PMID 34206599, 2021). "Furthermore, increased gene expression of vascular inflammation-related specific adhesion molecules ICAM-1 and VCAM-1 following IR injury, reflecting endothelial dysfunction, has been lessened by CM." (PMID 33627181, 2021). "Endothelial dysfunction is manifested by increased expression of adhesion molecules, e.g. C-reactive protein as well as, soluble vascular cell adhesion molecule-1 (sVCAM-1), intracellular adhesion molecule-1 (sICAM-1), and E-selectin, as was shown in type 1 diabetes (T1D) patients." (PMID 34603200, 2021). "The natural progression of DM is hyperglycemia, which contributes to oxidative stress, and pro-inflammatory markers, which lead to lipid peroxidation, increase the oxidative stress scenario, resulting in inflammation and increased VEGF, ICAM-1, VCAM-1, endothelial dysfunction, and apoptosis." (PMID 34012421, 2021).
endothelial dysfunction (continued). "Aggravated endothelial inflammation, which is characterized by overexpressed cytokines and adhesion molecules such as intercellular adhesion molecule-1 (ICAM-1), vascular cell adhesion molecule-1 (VCAM-1), and selectins, is an important pathological process in endothelial dysfunction." (PMID 34925018, 2021). "Intercellular adhesion molecule 1 (ICAM-1) and vascular cell adhesion molecule 1 (VCAM-1) are also important factors in the development of endothelial dysfunction and atherosclerotic plaque formation, by facilitating the transmission of leukocytes through the epithelium and their adhesion." (PMID 34685718, 2021). "Adhesion molecules, including ICAM-1 and VCAM-1, which may indicate endothelial dysfunction, are increased under conditions of high inflammation and oxidative stress." (PMID 34769353, 2021). "Indeed, in patients who presented graft failure, heme levels increased after 2 years, due to recurrence of hemolytic anemia and, probably, of the endothelial dysfunction, as supported by the VCAM-1 levels." (PMID 34956203, 2021). "Moreover, both play a pivotal role in the pathogenesis of CVD through endothelial dysfunction, recruitment of leukocytes due to increased adhesion molecules such as VCAM-1, and reactive oxygen species (ROS) production." (PMID 32998431, 2020). "Furthermore, ICAM-1 and VCAM-1 are characteristic molecules of endothelial dysfunction, which also illustrates the superior effects of BMMSCs for reducing hepatic sinusoidal endothelial and vascular endothelial injury." (PMID 32347385, 2020). "Enhanced vascular VCAM-1+ immune-reactivity in response to SAA is indicative of endothelial dysfunction and this may manifest as decreased bioavailability/bioactivity of vasodilating nitric oxide (NO)." (PMID 32075280, 2020). "An increase of one SD in the cMets score resulted in a 1.25-fold (95% CI 1.10–1.42) increase in the risk of acute inflammatory status and a 1.26-fold (95% CI 1.11–1.43) increase in the risk of endothelial dysfunction as defined by ICAM-1, while VCAM-1 showed a meaningless trend." (PMID 32433661, 2020). "Nitric oxide synthesis could be altered in EDS patients given the recent finding that markers of endothelial dysfunction such as VCAM-1, ICAM-1 and MCP-1 are increased in vEDS patients." (PMID 32933483, 2020). "Furthermore, plasma soluble VCAM-1, a surrogate marker for endothelial dysfunction, was sharply increased after 5/6 Nx and t-AUCB prevented this increase." (PMID 33777999, 2020). "Also, ICAM-1, VCAM-1 and E-selectin intervene with inflammatory cytokines of the vascular wall to promote extravasations and subsequent endothelial dysfunction." (PMID 32893859, 2020). "Additionally, Nrf2 activation has been implicated in the protective effects against different stimuli-induced VCAM-1 activation and endothelial dysfunction." (PMID 33274004, 2020). "With respect to circulating biomarkers, depression-linked type-D personality, that is, the combination of negative affectivity and social inhibition, has already been associated with endothelial dysfunction assessed by soluble ICAM-1 and VCAM-1, E-selectin, and VWF." (PMID 32230840, 2020). "This could be indicative of endothelial dysfunction and/or other mediators influencing VCAM-1 and E-selectin expression." (PMID 32934781, 2020). "Moreover, inflammatory markers TNFα and hs-CRP together with biochemical markers of endothelial dysfunction, ICAM-1 and VCAM-1, were also stratified according to GST risk genotypes." (PMID 31275451, 2019). "Circulating VCAM-1 has been shown to be a promising marker of endothelial dysfunction." (PMID 31369589, 2019). "The suppression of both ICAM-1 and VCAM-1 expression by Ginkgolide B indicates that this compound could alleviate Ox-LDL-induced endothelial dysfunction." (PMID 31281844, 2019).
endothelial dysfunction (continued). "Endothelial dysfunction in turn promotes vascular inflammation by inducing the production of adhesion molecules, like vascular cell adhesion molecule-1 (VCAM-1) and intercellular cell adhesion molecule-1 (ICAM-1), inflammatory mediators like cytokines, and vasoconstrictors." (PMID 29474366, 2018). "In Ghana, studies have been done in the area of epidemiology of SCD and its complications, but there is no report on the possible association between endothelial cell adhesion molecules (VCAM-1, ICAM-1 and E-Selectin) and endothelial dysfunction in SCD patients." (PMID 29690499, 2018). "Besides, a possible association between plasma levels of VCAM-1, ICAM-1, and E-Selectin, and endothelial dysfunction, exists in SCD patients." (PMID 29690499, 2018). "VCAM-1 has a significant correlation with TG and could play a significant role in endothelial dysfunction." (PMID 30246778, 2018). "Furthermore, levels of PTX3 correlate with other indicators of endothelial dysfunction such as the soluble VCAM-1 and vWf." (PMID 29435447, 2017). "Levels of TNFα (inflammation) or ICAM-1 and VCAM-1 (endothelial dysfunction) are classically elevated in these conditions and may therefore alter LpPLA2 activity." (PMID 28974763, 2017). "The biomarkers were representative of several biologic processes: apoptosis (soluble Fas), inflammation (soluble tumor necrosis factor receptor 1, interleukin 6, interleukin 8) and endothelial dysfunction, (angiopoietin 1, angiopoietin 2, and soluble vascular cell adhesion molecule 1)." (PMID 28814331, 2017). "In addition, we investigated the correlations between the levels of PA and LPA and the levels of the inflammatory and endothelial dysfunction biomarker soluble vascular cell adhesion molecule-1 (sVCAM-1)." (PMID 25496321, 2014). "It is not clear if the rise of AM and the decline of b- FGF levels may be consequences or predisposing factors for VCAM-1 and ICAM-1 elevation as these endothelial dysfunction biomarkers could reduce peripheral blood flow and vascular integrity." (PMID 25287126, 2014). "NF-κB is a redox-sensitive transcription factor of great potency for initiating and perpetuating the inflammatory response; its most important transcriptional product at the vascular level is VCAM-1, a marker both of inflammation and of endothelial dysfunction according to several authors." (PMID 23476105, 2013). "This suggests that augmented VCAM-1 expression may reflect inflammation and endothelial dysfunction and hence impairing the regulation of blood pressure." (PMID 22778962, 2012). "In addition to the previous study, the PPAR-α activator, docosahexaenoic acid (DHA), abrogated the development of hypertension, decreased ICAM-1, VCAM-1, corrected structural abnormalities, and improved the endothelial dysfunction induced by Ang II." (PMID 22848208, 2012). "As a complementary approach to evaluate a potential endothelial dysfunction in response to diabetes, the expression of VCAM-1, ICAM-1, P-selectin and E-selectin mRNA was measured in intact retinas of wt, ApoE−/−, TNFα−/− and ApoE−/−/TNFα−/− mice by real time RT-PCR." (PMID 20856927, 2010). "Concurrently, endothelial dysfunction, a hallmark of CSVD, is counteracted by DHA through enhanced NO bioavailability via AMPK activation, attenuated expression of adhesion molecules (ICAM-1/VCAM-1), and reduced endothelial lipotoxicity from triglyceride-rich lipoproteins." (PMID 40470292, 2025). "Moreover, further investigation into additional molecular pathways, such as oxidative stress markers, endothelial dysfunction mediators (e.g., VCAM-1, ICAM-1), and cytokine signaling pathways, would help clarify the underlying mechanisms of cigarette smoke-induced vascular injury." (PMID 40138141, 2025).
endothelial dysfunction (continued). "ICAM-1 and VCAM-1 are expressed on the cell surface and serve as cell adhesion molecules to mediate the transformation of monocytes and eosinophils into vascular endothelial cells, which exist in a soluble form in the plasma and are reliable markers of inflammation and endothelial dysfunction." (PMID 38251031, 2024). "It has been demonstrated that the soluble molecules VCAM-1, ICAM-1, and E-selectin were associated with the risk of mortality in an SCD cohort and are also correlated with the severity of pulmonary hypertension, a clinical manifestation of endothelial dysfunction." (PMID 38153527, 2024). "Notably, and in comparison with matched sedentary healthy controls, the collective cohort of patients (long COVID and ME/CFS) exhibited elevated levels of ET-1, VCAM-1, and TNF-α, as well as reduced levels of NOx, signifying underlying inflammation and endothelial dysfunction." (PMID 38600563, 2024). "As pulmonary adhesion molecules, ICAM1 and VCAM1, as lung adhesion molecules, bind to the endothelial surface and are involved in leukocyte infiltration through the ECs and into the lungs; their elevation is considered an early event in endothelial dysfunction." (PMID 39493864, 2024). "Regarding its effects on adhesion molecules, NAC revealed to inhibit VCAM-1 and ICAM-1 expression in hydrogen peroxide-stimulated HUVEC and visfatin-treated human microvascular endothelial cells (HMEC), underscoring that endothelial dysfunction is associated with oxidative stress." (PMID 37830604, 2023). "However, it is crucial to note that elevated VCAM-1 levels do not appear to pose a risk to healthy subjects in the absence of endothelial dysfunction." (PMID 38255155, 2023). "However, only treatment with BBR reduces TNFα-induced expression of vascular cell adhesion molecule-1 (VCAM-1) and intercellular adhesion molecule-1 (ICAM-1) associated with endothelial dysfunction, possibly through phosphorylation of MAPK/ERK1/2, compared to treatment with lovastatin." (PMID 38034996, 2023). "High glucose could increase the expression of endothelial dysfunction markers of VCAM-1, TNF-α, and VEGF-A, thus leading to the dysfunction of vascular endothelial cells in terms of tube formation, migration, and proliferation and pathological changes in the placental vascular structure." (PMID 36448064, 2022). "The adhesion molecule VCAM-1 plays a role in leukocyte adhesion and extravasation between endothelial cells, and the interaction between endothelial cells and leukocytes, and an increased reactive oxygen species production by the leukocytes result in endothelial dysfunction." (PMID 35204060, 2022). "However, adequate antihypertensive therapy decreases sVCAM-1 levels, suggesting that VCAM-1 could be a biomarker of endothelial dysfunction in patients with hypertension." (PMID 35222039, 2022). "As the endothelial dysfunction ensued, the proinflammatory cytokines may further activate the ECs, hence increasing the expression of adhesion molecules such as VCAM-1, ICAM-1, and even EC-derived MPs (EDMPs) subpopulation such as cluster differentiation 62 (CD62E) or E-selectin." (PMID 33718454, 2021). "In addition, long-chain n-3 PUFA may play an important role in improving the endothelial function, lowering circulating markers of endothelial dysfunction, such as E-selectin, vascular cell adhesion molecule-1 and intercellular adhesion molecule-1." (PMID 34371852, 2021). "Here, we report that in addition to endothelial dysfunction, diseased endothelial cells (ECs) were found to be pro-atherogenic and pro-inflammation due to high levels of ROS and Ox-LDLs, and high basal expressions of VCAM-1, in particular isoform b, respectively." (PMID 31641105, 2019). "This apparent dissociation between morphological and molecular data may be attributed to the fact that VCAM-1 was evaluated at the RNA level instead of the protein level, and it takes time to observe the consequences of endothelial dysfunction in lung morphology." (PMID 28542443, 2017).